RRM2 (ribonucleotide reductase regulatory subunit M2)
Diseases named in the same sentence as RRM2 in open-access papers (continued):
Sharing a sentence is not in itself a finding about the gene and the disease.
glioma (33 papers, 2016 to 2025). A benign or malignant brain and spinal cord tumor that arises from glial cells (astrocytes, oligodendrocytes, ependymal cells). "Bioinformatics investigation revealed the HEELPAR-hsa-let-7i-5p-RRM2 ceRNA network, which was linked to gliomas prognosis." (PMID 36750807, 2023). "Overexpression of RRM2 associated with genesis, progression of neuroblastoma, promotes tumorigenesis in glioblastoma, glioma and is a potential prognosis biomarker of these tumors." (PMID 38124207, 2023). "Notably, RRM2 is associated with metabolic adaptation to temozolomide by facilitating dNTP availability, particularly in glioma stem-like cells, which contributes to chemoresistance and recurrence." (PMID 39054369, 2024). "Similarly, high RRM2 expression (RRM2 high) analysis was associated with worsen survival of glioma, in general, and GBM patients, in particular." (PMID 27845331, 2016). "In glioma, cell death-related risk signatures (FANCD2, RRM2, BMP2, NFE2F2, MYD88) have been identified and validated using machine learning." (PMID 40559911, 2025). "In gliomas, in vivo and in vitro experiments have demonstrated that RRM2 enhances cell growth and migration while also increasing sensitivity to radiotherapy." (PMID 40625451, 2024). "RRM2 exhibited distinct expression profiles in various tumors and was significantly upregulated in gliomas." (PMID 36750807, 2023). "In glioma disease, RRM2 can promote human glioblastoma cell proliferation, migration and invasion and RRM2 expression controlled by BRCA1 can protect glioblastoma cells from endogenous replication stress while also increasing tumorigenicity." (PMID 36750807, 2023). "And through multiple analysis, the good predictive performance of HELLPAR/RRM2 axis for gliomas patients was confirmed." (PMID 36750807, 2023). "This study provides multi-layered and multifaceted evidence for the importance of HMMR and establishes a HMMR-related ceRNA (HEELPAR-hsa-let-7i-5p-RRM2) overexpressed network related to the prognosis of gliomas." (PMID 36750807, 2023). "The effectiveness of RRM2 in differentiating gliomas from normal tissues was assessed by ROC analysis, with an estimated AUC of 0.971 (95% CI: 0.962–0.979)." (PMID 36750807, 2023). "Clinical data analysis revealed that RRM2 expression in glioma patients was inversely correlated with the overall survival." (PMID 35651787, 2022). "RRM2 contributed to the proliferation and migration of glioma cells through the ERK1/2 and AKT pathways." (PMID 36566214, 2022). "Clinical data revealed that RRM2 is increased in GBM tissues and inversely correlated with glioma sufferers OS time, which suggests RRM2 as a potential therapeutic target, as well as a prognosis and predictive biomarker." (PMID 35651787, 2022). "RRM2 was reported to promote glioma proliferation and progression through ERK1/2- and AKT- signaling pathways." (PMID 34568059, 2021). "Together with the already described glioma biomarker, RRM2, we considered PLEK2 and GCSH as a novel WWOX-dependent biomarker triad of glioblastoma, whose subsequent investigation is advisable." (PMID 34204789, 2021). "It was found that ASPM, CCNB2, HSPG2, KLHDC8A and RRM2 mRNA were differentially expressed in glioma tissues of different grades." (PMID 32667745, 2020). "Spearman correlation analysis (SCA) for association revealed a positive correlation between the percentage of BRCA1+ and RRM2+ cells in our glioma cohort (correlation coefficient=0.24; P=0.0039)." (PMID 27845331, 2016). "Additionally, suppressing RRM2 is reported to be effective in prolonging survival in glioma patients." (PMID 40625451, 2024). "Time-dependent ROC analysis of RRM2 expression in gliomas patients suggusted that RRM2 could well predict the prognosis of gliomas patients at 1, 3 and 5 years." (PMID 36750807, 2023). "Finally, we need to further study the function and mechanism of HMMR and theHELLPAR/ RRM2 axis in gliomas by experiments." (PMID 36750807, 2023).
glioma (continued). "Given that this result was consistent with previous enrichment analyses, we speculated that the HMMR and RRM2 were involved in glioma disease progression by regulating cell cycle and proliferation." (PMID 36750807, 2023). "To verify the clinical significance of RRM2 in glioma patients, firstly, we performed IHC staining analysis, and founded that compared with normal human brain tissues, RRM2, CDK1, and p62 protein expression had increase in distinct grades of glioma, especially in GBM tissues." (PMID 35651787, 2022). "Also, results indicated that overall survival of different methylation levels of RRM2 exhibited a significantly different in thymoma, sarcoma, melanoma, and glioma." (PMID 36202136, 2022). "Our results revealed that RRM2 was a hazardous prognostic factor for glioma, and the subgroup with a higher expression level of RRM2 harbored more immune infiltration and expressed more immunotherapy-related markers, agreeing with the conclusions of previous studies." (PMID 36438805, 2022). "Both BRCA1 and RRM2 were determined to be negative prognostic factors for glioma patient survival and implicated in tumor development." (PMID 33804958, 2021). "Most have previously been proposed as biomarkers in a specific tumor (or tumor-related condition): C15orf48 in esophageal cancer, NF2 in neurofibromatosis, CMTM6 in renal adenocarcinoma, PLEK2 in lung adenocarcinoma, RRM2 in glioma, HOXA1 in breast and gastric cancers, and SAA2 in renal cancer." (PMID 34204789, 2021). "Our results provided a way to functionally explain the signaling of RRM2 during glioma progression." (PMID 32047515, 2019). "Next, we sought to determine whether there is a correlation between BRCA1 and RRM2 expression in our clinical glioma cohort." (PMID 27845331, 2016). "However, whether hsa-let-7i-5p participates in the development of gliomas by regulating RRM2 still needs further research to confirm." (PMID 36750807, 2023). "Enrichment analyses suggest RRM2’s role in glioma via cell cycle and proliferation pathways, indicating RHAMM and RRM2’s joint contribution to glioma progression through cell cycle regulation." (PMID 40806330, 2025). "Oncomine's comparative analysis between cancer and normal tissues revealed that both RRM2 and KIF23 were significantly overexpressed in glioma across various datasets, showcased in Fig.." (PMID 39248068, 2025). "Additionally, knockdown of the expression of BIRC5 (Spearman’s coefficients = 0.939, p < 0.001) and RRM2 (Spearman’s coefficients = 0.936, p < 0.001), two additional top 50 TK1-associated coexpressed positive genes, inhibits the migration, proliferation, and apoptosis of glioma cells." (PMID 36831773, 2023). "The genes RRM2, KIAA0101, UBE2C, LMX1A, DTL, and LBX1 demonstrated significant overexpression in all human glioma subtypes (GBM, ODG, OA, AA) with a p-value ≤ 0.0001." (PMID 31475119, 2019). "RRM2 had been found to promote the progression of human GBM and was a potential prognostic biomarker in glioma." (PMID 32047515, 2019). "We determined that RRM2 and COL3A1 were increased and directly correlated with glioma grade, while SH3GL2 and SNAP91 were decreased in GBM and inversely correlated with glioma grade." (PMID 27655637, 2016). "The validation study using the REMBRANDT glioma dataset (ALL gliomas and GBM) confirmed the prognostic significance of BRCA1 and RRM2 mRNA expression in malignant gliomas." (PMID 27845331, 2016). "In conclusion, this study provides multi-layered and multifaceted evidence for the importance of HMMR in gliomas and establishes a HMMR related ceRNA (HEELPAR-hsa-let-7i-5p-RRM2) overexpressed network of gliomas, which is better for understanding the link among lncRNA-miRNA-mRNA." (PMID 36750807, 2023). "More importantly, we examined the clinical data of patients with glioma in the CGGA database and revealed that RRM2 expression was inversely correlated with the OS time, indicating that RRM2 may be a prognosis marker of GBM." (PMID 35651787, 2022).
glioma (continued). "We determined that RRM2 and COL3A1 were up-regulated and directly correlated with glioma grade, while SH3GL2 and SNAP91 were down-regulated in GBM and inversely correlated with glioma grade." (PMID 27655637, 2016). "Additionally, RRM2 expression positively correlated with that of BRCA1 and both the percentage of BRCA1+ and RRM2+ cells correlated negatively with glioma patient survival, thus making RRM2 an attractive candidate for therapeutic targeting in GBM." (PMID 27845331, 2016). "To explore the therapeutic potential of targeting the BRCA1-RRM2 signalling axis in malignant gliomas, we performed immunohistochemistry (IHC) analysis BRCA1 and RRM2 in 145 gliomas and 10 non-neoplastic adult brain controls (NB)." (PMID 27845331, 2016). "Furthermore, we validated these findings by ‘in silico’ analysis of the publically available REMBRANDT glioma dataset (GlioVis web application), which confirmed the positive correlation between BRCA1 and RRM2 mRNA expression (SCA; P=0.00; CI 0.44–0.57)." (PMID 27845331, 2016). "The immunohistochemical analysis of RRM2 was positive in gliomas, but negative in normal tissues." (PMID 36750807, 2023). "Additionally, according to the CGGA data and qRT-PCR results, compared with non-tumor brain tissues, RRM2 mRNA expressions gradually increased with increasing the degree of glioma malignancy." (PMID 35651787, 2022). "For example, Ribonucleotide Reductase Regulatory Subunit M2 (RRM2) was a catalytic subunit of ribonucleotide reductase and functioned as a critical enzyme in the process of DNA replication and repair, and RRM2 has been proved negatively correlated with prognosis of glioma." (PMID 36438805, 2022). "The median RRM2 positivity (% of RRM2+ cells) in our cohort was 1% and Cox regression analysis showed that glioma patients negative for RRM2 (RRM2 negat., median survival not reached) had longer survival times than RRM2 positive patients (RRM2 positive; median survival=222 days, Log-rank P=0.00)." (PMID 27845331, 2016). "Importantly, our present results provide the first evidence of BRCA1 and its down-stream effector RRM2 as negative prognostic factors for glioma patient survival." (PMID 27845331, 2016). "However, previous studies of CAPG, FANCD2, HMOX1, HSPB1, RRM2, and STEAP3 did not develop any new clinical therapy in glioma." (PMID 36566214, 2022). "In addition, GCSH expression is clearly lowered with increasing glioma grade, while that of PLEK2 and RRM2 is clearly elevated; therefore, GCSH does not fit the premise of targeted therapy, i.e., biological pathway inhibition." (PMID 34204789, 2021). "We found that expression of up-regulated DEGs RRM2 and COL3A1 (>2-fold up-regulated as determined by the gene expression profile) was significantly higher in malignant gliomas compared to lower grade gliomas and non-tumor brain tissue and directly correlated with glioma grade." (PMID 27655637, 2016).
lung adenocarcinoma (32 papers, 2008 to 2025). A carcinoma that arises from the lung and is characterized by the presence of malignant glandular epithelial cells. "The findings demonstrated that high expression levels of MYBL2 and RRM2 were associated with shorter survival times in lung adenocarcinoma patients." (PMID 40885709, 2025). "Several studies have demonstrated that RRM2 is a potential diagnostic or prognostic biomarker for Ewing sarcoma, liver cancer, glioma, and lung adenocarcinoma." (PMID 38635758, 2024). "Souglakos' study revealed that the efficacy of docetaxel/gemcitabine in lung adenocarcinoma patients was associated with RRM2 mRNA expression from 42 patients." (PMID 33123291, 2020). "Ribonucleotide reductase subunit M1 and RRM2 mRNA expression in lung adenocarcinoma tumours is associated with clinical outcome to docetaxel/gemcitabine." (PMID 18414411, 2008). "In this study, we evaluated whether RRM2 gene expression is associated with the prognosis of patients with lung adenocarcinoma (LUAD) using publicly available data from The Cancer Genome Atlas (TCGA)." (PMID 33411689, 2020). "Previously, one study investigated the mRNA expression of RRM1 and RRM2 in tumors from patients with lung adenocarcinoma treated with docetaxel/gemcitabine." (PMID 40258059, 2025). "In lung adenocarcinoma (LUAD), high expression of RRM2 is regarded as a potential independent risk factor and correlated with immune infiltration." (PMID 38356717, 2024). "al displayed RRM2 was an independent prognostic factor in lung adenocarcinoma which was closely related oocyte meiosis." (PMID 38635758, 2024). "The study revealed that RRM2, SLC2A1, DDIT4, and VDAC2 were positively associated with the survival risk of lung adenocarcinoma patients." (PMID 39311766, 2024). "In lung adenocarcinoma, silencing RRM2 expression exerted anti-tumor effects by activating the cGAS/STING signaling pathway." (PMID 37056349, 2023). "Ribonucleoside-Diphosphate reductase subunit M2 (RRM2), one of the regulatory factors related to ferroptosis, affects the prognosis of lung adenocarcinoma through database analysis." (PMID 37369681, 2023). "RRM2, a cell cycle regulator, had an increased expression in lung adenocarcinoma with a poor prognosis." (PMID 35625619, 2022). "Immunohistochemistry (IHC) demonstrated that mRNAs DLGAP5, MCM7, RACGAP1, and RRM2 were upregulated in lung adenocarcinoma (LUAD)." (PMID 32149133, 2020). "In summary, high RRM2 expression is an independent predictive factor of poor prognosis in patients with lung adenocarcinoma." (PMID 33411689, 2020). "The mRNA expression of RRM1 and RRM2 in tumours from lung adenocarcinoma patients treated with docetaxel/gemcitabine was assessed and the results correlated with clinical outcome." (PMID 18414411, 2008). "The present study has demonstrated for the first time a positive correlation between tumour mRNA expression of RRM2 and response to a gemcitabine-based combination in patients with lung adenocarcinomas." (PMID 18414411, 2008). "In conclusion, the results of the present study revealed that the efficacy of docetaxel/gemcitabine in lung adenocarcinoma patients is associated with RRM1 and RRM2 mRNA expression, thus indicating the importance of tailoring treatment." (PMID 18414411, 2008). "To further investigate this issue, we have carried out a multicentre phase II study to evaluate the impact of RRM1 and RRM2 mRNA expression in the tumours of lung adenocarcinoma patients treated with docetaxel/gemcitabine." (PMID 18414411, 2008). "RRM2 was determined as a promising metabolic checkpoint for lung adenocarcinoma." (PMID 35898471, 2022). "In another lung study, a mutation - caused by a T to A substitution and consequent valine (V) to glutamic acid (E) substitution within the second RRM (RRM2) of RBM10 - was reported in A549 lung adenocarcinoma cells, with consequences for NUMB alternative splicing." (PMID 25889998, 2015).
lung adenocarcinoma (continued). "We utilized three lung adenocarcinoma databases, TCGA LUAD data, GSE31210 and GSE30219, alongside the human transcription factors (TFs) database to identify the transcription factors of RRM2." (PMID 40885709, 2025). "Clinical staging revealed a positive correlation between higher stages of lung adenocarcinoma and increased staining intensity of MYBL2 and RRM2." (PMID 40885709, 2025). "All showed a very strong correlation between MYBL2 and RRM2, indicating that MYBL2 probably functions as a transcription factor of RRM2 in lung adenocarcinoma." (PMID 40885709, 2025). "We employed a tissue microarray (TMA) containing 78 lung adenocarcinoma samples with complete clinical information and performed immunohistochemical (IHC) staining of MYBL2 and RRM2." (PMID 40885709, 2025). "Inhibition of RRM2 can activate STING signaling pathway and inhibit the enhancement of radiosensitivity of lung adenocarcinoma." (PMID 34630529, 2021). "However, the role of RRM2 in lung adenocarcinoma (LUAD) remains unclear." (PMID 33123291, 2020). "Moreover, in lung adenocarcinoma, the predicted OCG RRM2, which we also identified as a prognostic gene above, interacted with one inhibitor, gemcitabine." (PMID 40258059, 2025). "Intriguingly, transgenic mice developed lung adenocarcinoma but not other tumors in the presence of RRM2 overexpression." (PMID 19002265, 2008).